INS (insulin)
Diseases named in the same sentence as INS in open-access papers (continued):
Sharing a sentence is not in itself a finding about the gene and the disease.
type 2 diabetes (continued). "However, individuals who are not obese on the basis of height and weight can, like people with overt obesity, be hyperinsulinemic, insulin-resistant, and predisposed to type 2 diabetes, hypertriglyceridemia, and premature coronary heart disease." (PMID 37183008, 2023). "In type 2 Diabetes, β-cell failure is caused by loss of cell mass, mostly by apoptosis, but also by simple dysfunction (dedifferentiation, decline of glucose-stimulated insulin secretion)." (PMID 37306934, 2023). "In addition, this fold has been previously associated with an increased risk of developing arterial hypertension and type 2 diabetes, which is consistent with the results found regarding insulin resistance and blood pressure values." (PMID 37763094, 2023). "The hallmark of type 2 diabetes progression is the progressive decline of pancreatic beta-cell mass and secretory function with subsequent worsening glycaemia, secondary oral hypoglycaemic agent failure, and initiation of insulin therapy." (PMID 37858088, 2023). "Particularly in type 2 diabetes, oxidative and endoplasmic reticulum (ER) stress in pancreatic β-cells caused by glucotoxicity, lipotoxicity, and glucolipotoxicity lead to dysfunction of insulin secretion from pancreatic β-cells." (PMID 38249612, 2023). "The majority of cases of type 2 diabetes are characterized by a deficiency in insulin synthesis, secretion, or action, which is caused by the inability of pancreatic beta cells to produce enough insulin." (PMID 37233655, 2023). "It is associated with higher fasting insulin concentrations and predisposes to type 2 diabetes." (PMID 36409629, 2023). "Obesity and type 2 diabetes are associated with defects of insulin action in different tissues or alterations in β-cell secretory capacity that may be triggered by environmental challenges, inadequate lifestyle choices, or an underlying genetic predisposition." (PMID 36768391, 2023). "Therefore, this study confirmed that with body weight loss, serum triglyceride, cholesterol, FFA, insulin, and glucose levels were tightly associated with type 2 diabetes and significantly increased in HFD/STZ rats." (PMID 37823118, 2023). "After a quality control process, we obtained 10 SNPs strongly associated with 2-h Glucose, 47 SNPs strongly associated with Fasting Glucose, 26 SNPs associated with Fasting Insulin, and 105 strongly associated with Type-2 Diabetes from GWAS and 68 SNPs closely related to Fasting Glucose." (PMID 38179409, 2023). "Type 2 diabetes (T2D) is caused by insufficient insulin secretion from pancreatic β cells." (PMID 36656641, 2023). "Corroborating this pathophysiologic mechanism, in the study by Strawbridge and colleagues on subjects with type 2 diabetes and controls, sCD93 levels were inversely associated with BMI, insulin, and the HOMA index and positively correlated with adiponectin levels." (PMID 37371490, 2023). "Therefore, it provides a target for designing inhibitors that will enable β-cell regeneration—leading to a reduction in insulin producing cell loss in type I diabetes (T1D) and increased insulin production in type II diabetes (T2D)." (PMID 37195917, 2023). "Moreover, low levels of IGFBP2 were described in patients with type 2 diabetes, while higher levels are associated with insulin sensitivity." (PMID 36586437, 2023). "Also, genes that were up-regulated after induced methylation of the Arx promoter were associated with a few pathways including Type II diabetes mellitus and Insulin secretion pathways." (PMID 37008919, 2023). "Various studies indicate that taurine might help improve insulin sensitivity, making it beneficial for individuals with type 2 diabetes (T2D) or those at risk of developing the condition." (PMID 37836520, 2023). "Carbohydrates have a much greater effect on insulin secretion than proteins or fats, and low carbohydrate diets are effective in reducing weight loss, reducing risk factors for cardiovascular disease, and improving type 2 diabetes." (PMID 36771475, 2023).
type 2 diabetes (continued). "Increased expression and activation of GSK-3 have been observed in the skeletal muscle of rodent models of obesity and obese individuals with type 2 diabetes, and this dysregulation is associated with impaired insulin-mediated glucose disposal and glycogen synthase activation." (PMID 37630316, 2023). "The disruption of the 24 h circadian rhythm with subsequent lower nocturnal melatonin secretion is associated with insulin secretion and resistance, which may influence the development and progression of type 2 diabetes." (PMID 36959654, 2023). "On top of reducing hyperglycemia and improving insulin action, pioglitazone or rosiglitazone treatment of individuals with type 2 diabetes (T2DM) was associated with remarkable improvements in plasma triglyceride and HDL-C levels and in LDL particle concentration and size." (PMID 37893070, 2023). "Recent innovations, including the introduction of antidiabetic drugs with proven cardiorenal benefits, highly effective agents for inducing weight loss, and more convenient insulin regimens and glucose sensors are having a profound impact on the everyday lives of patients with type 2 diabetes." (PMID 37700155, 2023). "The glucagon-to-insulin ratio is strongly linked to hyperglycemia in patients with type 2 diabetes." (PMID 37960324, 2023). "In addition, many individuals with low HDL cholesterol display elevated fasting-plasma-insulin levels, resistance to exogenous insulin in euglycemic clamp studies, and an increased risk of Type 2 diabetes." (PMID 36830597, 2023). "However, carriers of the rs112498319 type 2 diabetes risk allele (C) showed lower mean glucose-stimulated insulin secretion levels." (PMID 36633628, 2023). "The fetal insulin hypothesis proposes that the association between low birthweight and type 2 diabetes could be confounded by genetic factors underlying both low birthweight and increased type 2 diabetes risk." (PMID 37303007, 2023). "This study used the MR method for the first time to explore the causal relationship between the characteristics of Fasting Glucose (including 2-h Glucose, Fasting Glucose, Fasting Insulin, Type-2 Diabetes, and HbA1c) and the risk of Melanoma from the perspective of genetics." (PMID 38179409, 2023). "Moreover, recent studies have shown that circulating levels of FGF-21 are strongly associated with insulin-resistant states such as obesity and type 2 diabetes and inversely associated with both whole-body (muscle) and hepatic insulin sensitivity." (PMID 35883694, 2022). "We examined in persons with type 2 diabetes (T2D) whether the use of insulin and the risk of serious hypoglycemic events with insulin is higher in persons with more advanced CKD." (PMID 35189851, 2022). "Physiological and pharmacological data have shown that activation of the GLP‐1 receptors promotes insulin secretion from pancreatic beta cells and also causes weight loss and thus representing a significant pharmacological target for the treatment of type 2 diabetes." (PMID 34519026, 2022). "The fetal insulin hypothesis proposed that insulin secretion and resistance, genetically determined, can affect intrauterine growth and explain the association between lower birthweight and type-2 diabetes later in life." (PMID 36139771, 2022). "Mutations in the INS gene can be associated with a broad spectrum of clinical presentations, varying from intrauterine insulin deficiency and permanent neonatal diabetes to mild young- and adult-onset diabetes." (PMID 36294752, 2022). "However, GEO DataSet (GDS158) was just a search for susceptibility genes for type 2 diabetes using insulin-sensitive and insulin-resistant instead of the CADs-related ones studied in this study." (PMID 35090550, 2022). "The management of patients with type 2 diabetes may include diet and lifestyle modifications, frequently in association with oral hypoglycemic drugs and, in some cases, subcutaneous insulin therapy." (PMID 36235503, 2022).
type 2 diabetes (continued). "The unique signaling mechanism of DPP-IV inhibitors, which involves delaying the degradation of incretin hormones (GLP-1 and GIP), causing decrease in glucagon release, and improving insulin secretion, has demonstrated a significant impact on the treatment of type 2 diabetes." (PMID 36005629, 2022). "Interestingly, the ABCC8 locus and specifically the variant rs3758953 in this study have been reported to be associated with type 2 diabetes, and the carriers of the risk genotypes of rs3758953 had higher levels of both glucose and insulin." (PMID 35474489, 2022). "Second, elevated levels of TNF- α and IL-6 that have been linked with obesity and type 2 diabetes might impair insulin sensitivity by inhibiting insulin signaling pathways." (PMID 36213511, 2022). "Therefore, aerobic exercises are methods to decrease insulin resistance and the risk for developing type 2 diabetes, particularly in obese individuals." (PMID 36110558, 2022). "Previous studies reported that the association between rs5219 and increased type 2 diabetes risk could be partly explained by a reduced insulin secretion resulting from rs521923,24." (PMID 36456687, 2022). "Evidence suggests that high concentrations of fatty acids and glucose in obesity trigger glucolipotoxic responses that gradually impair the ability of β-cell to provide insulin due to dedifferentiation or altered mass, which is a hallmark of late-stage type 2 diabetes mellitus." (PMID 35789435, 2022). "Overall, elevated serum retinol might increase the risk of type 2 diabetes which is mainly mediated by increased insulin resistance, TG, or serum XO activity." (PMID 35425797, 2022). "Thus, data from human volunteers confirms a wide variance in first-pass hepatic insulin extraction and supports the idea that lower insulin clearance is characteristic of individuals at increased risk for type 2 diabetes." (PMID 35163746, 2022). "Thus, it is a remarkable set of circumstances that have led our laboratory to return to insulin degradation as a possible pathogenic factor in type 2 diabetes." (PMID 35163746, 2022). "Many middle-aged Japanese may be at high risk of type 2 diabetes due to a decrease in basal insulin secretion." (PMID 36432554, 2022). "However, in the present study, the positive association between CT-proET-1 and incident type 2 diabetes remained stable after additional adjustment for eGFR, insulin, hsCRP, leptin, and fasting glucose suggesting other possible explanations." (PMID 35681200, 2022). "Type 2 diabetes is caused by the body’s insulin failing to function properly." (PMID 35742015, 2022). "Type 1 diabetes originates from autoimmune disease leading to destruction of pancreatic β-cells and consequently deficiency in insulin while type 2 diabetes attributes to insulin resistance and hence alters the metabolism of carbohydrates, proteins, and lipids." (PMID 35326092, 2022). "The strongest evidence is for antipsychotics, which may increase the risk of type 2 diabetes indirectly (e.g. through weight gain) or directly by impairing insulin sensitivity." (PMID 35729420, 2022). "Serum concentration of ADAM10 is increased in type 2 diabetes and is associated with glycemia and insulin therapy, which may potentially affect the specificity of systemic ADAM10 level as a biomarker." (PMID 35705192, 2022). "In recent years, glucagon-like peptide- 1 (GLP 1) analogue injectable treatment for type 2 diabetes has been introduced to overcome some potential barriers associated with insulin medication initiation and adherence, such as weight gain and injection frequency and hypoglycemia." (PMID 36556420, 2022). "An imbalance between glucose consumption and insulin release is the cause of type-2 diabetes." (PMID 36339037, 2022). "Thus, the mechanism of insulin dysfunction in 17α-hydroxylase/17,20-lyase deficiency is probably different from that of type 2 diabetes." (PMID 35937831, 2022).
type 2 diabetes (continued). "Epigenetic biomarkers may reflect age-related DNA methylation changes in pancreatic cells and are associated with insulin secretion in vivo and type 2 diabetes." (PMID 35336242, 2022). "In terms of glucose action, glucose-lowering medications target insulin secretion and muscle, liver, and adipose tissue IR to different degrees and sub-phenotyping individuals at risk of type 2 diabetes may prove advantageous in targeting treatment." (PMID 36557310, 2022). "Consequently, disturbed clustering for a variety of reasons has been described as a mechanism underlying the impaired kinetics of insulin secretion in type 2 diabetes or its disease models." (PMID 36120467, 2022). "A diminished insulin response, often described to be more prominent during the first phase, but also recognizable during the second phase is associated with the manifestation of type 2 diabetes or models of this disease." (PMID 36120467, 2022). "For example, defects in insulin secretion cause maturity-onset diabetes in the young (MODY)." (PMID 35879296, 2022). "Based on the effects of thyroid hormones on the metabolism of carbohydrates, lipids, and insulin secretion, the association between thyroid function and type 2 diabetes has long been hypothesized." (PMID 35137143, 2022). "Our findings based on MR studies support a weak association between smoking and type 2 diabetes, an association that might be related to reduced insulin sensitivity among smokers." (PMID 35816897, 2022). "There may be an association of the tissue level of LCN-2 with insulin sensitivity and glucose homeostasis as it is increased in obesity and type 2 diabetes." (PMID 36362238, 2022). "One study reported that among participants with a higher risk for type 2 diabetes, increasing oral processing time of fried rice led to a greater bolus fragment surface area, more saliva uptake in bolus and higher postprandial glucose and insulin responses." (PMID 35773354, 2022). "Furthermore, m6A sequencing was performed in human type 2 diabetes islets, and sequencing analysis showed that multiple hypomethylated transcripts were associated with insulin secretion, the insulin/IGF1 signalling pathway and cell cycle progression." (PMID 36407103, 2022). "However, remission cats did have an increase in fasting insulin, which in human type 2 diabetic is associated with a decrease in adiponectin, but this was not demonstrated in remission cats." (PMID 35968003, 2022). "We have suggested an alternative hypothesis—that reduced insulin clearance is a causative factor in risk for type 2 diabetes." (PMID 35163746, 2022). "Vitamin K2 (menaquinones) may improve insulin sensitivity via several pathways and has been associated with reduced type 2 diabetes risk." (PMID 35276774, 2022). "Other aspects potentially contributing to the pathogenesis of type 2 diabetes in mHC are GC’s influence on the adipokines secretion, such as adiponectin and leptin, which may have a relevant impact on insulin sensitivity and GR genetic variants." (PMID 35054858, 2022). "Interestingly, although caffeine acutely impairs insulin sensitivity, many observational studies have found that regular consumption of coffee was associated with a lower risk of type 2 diabetes (T2D)." (PMID 35990317, 2022). "While histidine may have some beneficial health effects (i.e., antioxidant activity), histidine metabolites and related imidazole derivatives may be associated with impaired insulin signaling, type 2 diabetes, and kidney disease." (PMID 35277064, 2022). "In addition, when compared with older adults with type 2 diabetes, type 2 diabetes before age 45 appears to be a more aggressive disease with an increased risk of requiring insulin." (PMID 39131121, 2022).
type 2 diabetes (continued). "However, higher prevalence of the metabolic syndrome, obesity, fibromyalgia, anxiety, depression, increased waist circumference, increased risk of type 2 diabetes, and elevated levels of C-peptide and insulin are found in IBS patients compared to controls." (PMID 35565656, 2022). "Type 2 diabetes and abnormalities in insulin secretion and glucose levels have been linked to AN." (PMID 35013117, 2022). "The objective of this study is to investigate the roles of cardiometabolic factors (including blood pressure, blood lipids, thyroid function, body mass, and insulin sensitivity) in mediating the causal effect of type 2 diabetes (T2DM) on cardiovascular disease (CVD) outcomes." (PMID 35282373, 2022). "Therefore, HFD is associated with type 2 diabetes and leads to Alzheimer’s disease (AD) by increasing diabetic cognitive dysfunction due to insulin resistance." (PMID 36014555, 2022). "Type 2 diabetes is characterized by a combination of early insulin resistance and progressive loss of pancreatic β-cell function, resulting in insufficient amounts of insulin and subsequent hyperglycemia." (PMID 36500649, 2022). "The question arises whether there are any longitudinal data which might support the hypothesis that lower insulin degradation is pathogenic for type 2 diabetes." (PMID 35163746, 2022). "People with KPD have clinical features of type 1 and type 2 diabetes and have sporadic periods of insulin requirement marked by insulin deficiency, which may lead to severe ketosis if not appropriately treated." (PMID 35462815, 2022). "Type 2 diabetes results from poorly understood processes that cause resistance to insulin stimulation and gradual loss of glycaemic control, which can be accompanied by reduced insulin production." (PMID 35178244, 2022). "Thus, there is an apparent association between insulin clearance and risk for type 2 diabetes in different ethnic groups." (PMID 35163746, 2022). "Thus, these two studies unequivocally determine the effect of CB1R activation in beta-cell apoptosis and therefore insulin signaling deficiency and the development of type 2 diabetes." (PMID 35328503, 2022). "For example, type 2 diabetes (T2D) is a metabolic disease caused by the functional decline and/or loss of peripheral insulin signaling, ultimately resulting from the inability of pancreatic beta cells to secrete enough insulin to maintain glucose homeostasis." (PMID 36197983, 2022). "In addition, TMEM163 was also shown to be highly expressed in insulin secretory vesicles in human pancreas, and has been identified as a risk factor in type 2 diabetes." (PMID 35901096, 2022). "Insulin resistance and decreased insulin production caused bypancreatic beta-cell dysfunction are the two primary disorders of type 2 diabetes mellitus.However, it is evident that the disease process is heterogeneous and consists of other pathogenic components." (PMID 37701508, 2022). "In this study, we observed a modest decrease of C-peptide at the late phase of OGTT in participants consuming brown seaweed extract, suggesting a potential for reduced insulin secretion in the long term, thereby decreasing the risk for developing glucose intolerance and type 2 diabetes." (PMID 35323474, 2022). "Uncoupling of downstream insulin signalling at the PI3k-Akt-mTOR axis in various cell types including hepatocytes and adipocytes has been directly implicated in the development of insulin resistance and type 2 diabetes." (PMID 35327652, 2022). "When BW and PW were analysed together in the same survival model, the effect of PW was attenuated, suggesting that the association between offspring PW and parental type 2 diabetes may be mediated by fetal insulin dysfunction alleles." (PMID 35951032, 2022).